BMI1 (BMI1 proto-oncogene, polycomb ring finger)
Diseases named in the same sentence as BMI1 in open-access papers (continued):
Sharing a sentence is not in itself a finding about the gene and the disease.
cancer (continued). "Despite not being HNSCC-specific, the results are consistent with previous research employing various cancer models and raise the prospect of a therapeutic window for Bmi-1 targeting." (PMID 39866230, 2025). "By focusing on epigenetic alterations, particularly PRC1/Bmi‐1 deregulation, our present review does address a crucial and emerging area of cancer research, highlighting the significance of epigenetic factors in GBM pathogenesis." (PMID 39791545, 2025). "Bmi‐1 is an oncoprotein prerequisite for transformation, metastatic migration, and malignancy maintenance in multiple cancer models." (PMID 39791545, 2025). "Possibly the best-described Bmi-1 function in cancer pathogenesis is most convincingly reported in the context of hematopoietic and central nervous system malignancies." (PMID 39866230, 2025). "BMI1 has been functionally characterized as a pleiotropic oncogene across diverse cancer types, driving tumor progression and therapeutic resistance through epigenetic modulation of specific transcriptional programs." (PMID 40623983, 2025). "BMI1 is known to regulate the cell cycle and cellular DNA repair capacity; its overexpression is often observed in human cancers and known to act in an oncogenic fashion to drive stem-like properties that favor proliferation." (PMID 40568127, 2025). "As an oncogene, BMI-1 allows cancer cells to evade apoptosis by modulating multiple growth signaling pathways." (PMID 41345229, 2025). "Further, miR-320a targets Bmi-1 directly and prevents carcinoma of the Nasopharynx cases from expressing it, suggesting that different miRNAs can impact the mRNA of Bmi-1 in varying cancer situations, underscoring its significance." (PMID 39866230, 2025). "It is well known that Myc, Sp1, BMI1, and MALAT1 are cancer stem cell (CSC) markers implicated in chemoresistance in NSCLC." (PMID 38125755, 2024). "BMI1 mainly maintains cell stemness to promote cell proliferation and migration during invasion in various cancer cells." (PMID 39707202, 2024). "We also performed double immunofluorescence staining for pSmad2/3L-Thr and Bmi1, a representative marker for slow-cycling (cancer) stem cells." (PMID 37511456, 2023). "PTC-209 significantly decreased the percentage of BMI + cancer stem cells and its combination with cisplatin reduced both BMI1 + and bulk cancer cells in vivo." (PMID 37453969, 2023). "By elevating ROS and DNA damage levels in the cell, Cisplatin is likely activating Bmi-1 for response to these stimuli, inadvertently activating cancer cell stemness properties." (PMID 36726797, 2023). "Bmi-1, a polycomb complex protein, has been established as a pivotal player in controlling cancer cell stemness." (PMID 36726797, 2023). "Recently, Grembecka and Cierpicki's laboratory developed the small molecule RB‐3 that inhibits RING1B/BMI1‐mediated H2A ubiquitination in cancer cells." (PMID 36881608, 2023). "The reported deubiquitinases of MYC include USP22, USP28, USP29, USP36 and USP37, and they enhance cancer stemness via BMI1, LSD1 Snail and CEP63 stabilization, respectively." (PMID 36765885, 2023). "B-cell-specific Moloney murine leukemia virus integration site 1 (Bmi-1) is overexpressed in various cancer types." (PMID 37219449, 2023). "Considering that the EMT facilitates the invasion and metastasis of a variety of cancer types, we evaluated epithelial and mesenchymal marker expression after silencing endogenous Bmi-1 in NPC cells." (PMID 37219449, 2023). "Altogether, while Bmi-1 regulation in cancer isn't necessarily conserved as compared to its physiological regulation, these findings highlight Bmi-1 as an important player in tipping the scales between health and disease." (PMID 36726797, 2023). "Comparable to the effect of Cisplatin, treatment with Metformin (diabetes drug that has exhibited anticancer properties in various other cancers) lead to a reduction in bulk tumor cells but an increase in CSCs and Bmi-1 expression in HNSCC." (PMID 36726797, 2023).
cancer (continued). "Mechanistic investigation found that, by interacting with the E3 ligase of BMI1, ZDHHC18 blocked degradation of BMI1, a gene contributing to the maintenance and renewal of cancer-initiating stem cells, and, thus, maintained the self-renewal capacity of GSCs." (PMID 37759431, 2023). "Bmi-1 overexpression has been reported in a plethora of cancers, including gastric, ovarian, breast, head and neck, pancreatic, lung, hepatocellular, and endometrial carcinoma and correlated with a variety of indicators of poor prognoses." (PMID 36726797, 2023). "Another paradoxical relationship has been observed between Bmi-1 and Hox signaling pathways in cancer." (PMID 36726797, 2023). "A direct relationship between the Akt pathway regulation of Bmi-1 is also observed in various cancer cells." (PMID 36726797, 2023). "B lymphoma Mo‐MLV insertion region 1 (BMI1) has been shown to be an oncogene in various cancers including BLCa." (PMID 36208024, 2023). "This also strongly implicates Bmi-1 as a powerful point of convergence in multiple therapeutic resistance mechanisms of different treatment modalities across many cancers." (PMID 36726797, 2023). "Existing research indicates that BMI1 helps maintain the self-renewal characteristics of normal stem cells and cancer cells." (PMID 37333449, 2023). "These contrasting findings illuminate the complex dysregulation of Bmi-1 in cancer, highlighting the need for further research in this area." (PMID 36726797, 2023). "In tumorigenesis, BMI1 plays important roles in promoting cancer stemness, leading to tumor metastasis, recurrence, and drug resistance." (PMID 36199791, 2022). "Bmi-1 can regulate transcription, affect cell proliferation, and participate in the formation of the malignant tumors by RING finger binding to other critical proteins." (PMID 35897796, 2022). "Taken together, these results showed that BMI1 correlates with cancer stemness is required for tumour initiation in LAC cells." (PMID 35794816, 2022). "Since CD44 and BMI1 are well known cancer stem cell markers, we also investigated the effect of miR-3928 on GBM stem cells (GSCs)." (PMID 35409289, 2022). "BMI1 upregulation in multiple cancer types and a described role in cancer stem cells (CSCs) has led to the development of pharmacological inhibitors." (PMID 36497341, 2022). "To extend the cellular effect of NDG1 to molecular presentations, we determined the expression of cancer stemness-associated regulators (ABCG2, Twist1, BMI1, NES, c-Met) in NDRG1-FL-transfected HNC cells." (PMID 35563887, 2022). "We found that DHEA reduced HNSCC cell viability, suppressed sphere formation, and inhibited the expression of cancer-stemness markers, such as BMI-1 and Nestin." (PMID 35912234, 2022). "Bmi-1 (polycomb complex protein) is an oncogene which allows cancer cells to escape apoptosis through several signaling pathways involved in cell growth." (PMID 35250573, 2022). "miR-203 induces apoptosis in YD-38 cells by directly targeting Bmi-1, which suggests its possible application as an anti-cancer therapeutic." (PMID 35898889, 2022). "While BMI1 is a potential therapeutic target, the development of BMI1 inhibitor for cancer treatment is still in the beginning stage." (PMID 35794816, 2022). "We have previously found that the transcriptional repressor BMI1, which is an important regulator of self-renewal, linked to EMT and metastasis in different cancers including PDAC, is an effector of SOX9 activity." (PMID 35205666, 2022). "Recently, we found that the expression of Bmi-1 was significantly greater in GAC tissues than in the matched histologically cancer-free specimens (unpublished data)." (PMID 35415241, 2022). "In the past two decades, many researchers have discussed the relationship between the expression level of Bmi-1 and the clinical characteristics of different cancers." (PMID 35897796, 2022).
cancer (continued). "The overexpression of BMI-1 and its increased protein stability mediated by PTMs, such as O-GlcNAcylation, participate in the self-renewal of cancer cells and the progression of prostate cancer." (PMID 35046519, 2022). "qPCR analysis showed high levels of ChgA, Bmi1, and glycolytic gene expression in Pdk1-mCherry+ cells compared to Pdk1-mCherry−, indicating that pPDH+ cancer cells exhibit the same cell phenotype than pPDH+ cells in the normal epithelium." (PMID 35314684, 2022). "Targeting cancer stemness mediated by BMI1/MCL1 with BI‐44 provides the basis for a new therapeutic approach in NSCLC treatment." (PMID 35794816, 2022). "In recent years, additional downstream pathways of BMI1 have been identified in some other types of tumors, suggesting a broader and more complex role played by BMI1 in tumorigenesis and cancer progression." (PMID 35346195, 2022). "Bmi-1 is expressed in almost every human tissue and in many cancers, and serves as a biomarker for some cancers." (PMID 35897796, 2022). "The miR-200c suppressed growth and induces differentiation in cancer cells, whereas in the normal mouse gland, it suppresses the expression of BMI1 and the ability of mouse mammary repopulating units (MRUs) to develop outgrowths." (PMID 36555241, 2022). "The function of Bmi-1 in tumors has been identified in various pathological processes, including abnormal cell proliferation, evasion of apoptosis, migration of cancer cells, and stemness maintenance of cancer stem cells (CSCs)." (PMID 35897796, 2022). "Collectively, these combined data suggest that JNK signalling plays a key role to link oncogenic pathway or environment stress to cancer stemness, regulating self‐renewal and chemo‐resistance through modulation of protein stability of BMI1 in LAC cells." (PMID 35794816, 2022). "In particular, we focus on the pathological processes of Bmi-1 in cancer, and explore the clinical relevance of Bmi-1 in cancer biomarkers and prognosis, as well as its implications for chemoresistance and radioresistance." (PMID 35897796, 2022). "Although a few results are contradictory, most of the results prove the importance of Bmi-1 in the occurrence and development of cancer." (PMID 35897796, 2022). "The authors found BMI1, among other CSCs-related (cancers stem cell) markers, up regulated in the CD133+ cells when compared to the negative cell population." (PMID 36289829, 2022). "We have revealed that BMI1 exerts its cancer-promoting effect by mediating transcriptional repression of SIK1, which provides a potential therapeutic target for OS." (PMID 35346195, 2022). "Both cell lines had medium positive staining for the proliferation marker Ki67 (an average of 47.9 ± 7.9% and 15.5 ± 4.7%, respectively) and a high positive staining for the cancer biomarker BMI1 (an average of 82.7% and 64.6%, respectively)." (PMID 36482387, 2022). "The existing literature suggests a significant BMI1 function in malignancy and its upregulation in different cancers." (PMID 35845311, 2022). "Previous studies have shown that BMI1 regulates a variety of gene expressions and signalling pathways in different types of tissue stem cell or cancer." (PMID 35794816, 2022). "PcG family member Bmi-1 plays a vital role in the proliferation, apoptosis, metastasis, and chemical sensitivity of cancer cells." (PMID 35897796, 2022). "Upregulation of Bmi-1 was observed in various types of cancer and is a potent stimulator of stem cell regeneration." (PMID 36793341, 2022). "BMI1 has been documented to regulate a number of genes in cancers, among which PTEN, phosh‐AKT (pAKT) and p16INK4A were highly associated with oncogenesis." (PMID 35794816, 2022). "We focused on B-cell-specific Moloney leukemia virus insertion site 1 (BMI1), since the BMI1 gene is known to be a poor prognostic factor in several cancers." (PMID 36139536, 2022).
cancer (continued). "Alterations in the expression and activity of BMI-1 are responsible for the incorrect expression of many other genes that control cell division, proliferation, apoptosis, and cell migration leading to cancer onset and progression." (PMID 36497428, 2022). "The molecular regulation of cancer stemness-related biomarkers/regulators (BMI1, NES, and c-Met) was also examined in OECM1 cells." (PMID 35563887, 2022). "Increasing evidence has indicated that Bmi-1 plays a critical role in the self-renewal and differentiation of cancer stem cells." (PMID 35897796, 2022). "Por ende, Bmi1 es un posible blanco terapéutico para las células troncales cancerígenas de este carcinoma." (PMID 38389655, 2022). "Overexpression of BMI1 cells in humans correlates with the advanced stage of cancer, tumor metastasis, poor prognosis, and resistance to radiation and chemotherapy." (PMID 33927214, 2021). "Zinc‐finger E‐box‐binding homeobox 1 (ZEB1) is an important regulator of epithelial‐mesenchymal transition (EMT) and is involved in the maintenance of cancer stem cells (CSCs) via miR‐200c and BMI1 pathway." (PMID 33764690, 2021). "Along with other studies, we have previously shown that Bmi-1, an oncogene overexpressed in various human cancers in relation with enhanced proliferation and metastasis, has a vital role in autophagy and ROS generation." (PMID 34510030, 2021). "It has been recently demonstrated that Bmi-1+ cancer stem cells mediate chemoresistance and metastasis in HNSCC." (PMID 34689150, 2021). "BMI-1 plays a role in the self-renewal ability of stem cells, and high expression in cancer was related to epithelial-mesenchymal transition (EMT) and poor prognosis." (PMID 34287293, 2021). "BMI1 is known to play a key role in the regulation of stem cell self-renewal in both endogenous and cancer stem cells." (PMID 34442383, 2021). "In this study, pharmacological inhibition (PTC596) or knockdown (siRNA) of BMI-1 reduced cancer stem-like cells and enhanced cancer cell death." (PMID 34576269, 2021). "Many studies have demonstrated that BMI1 can stimulate cancer initiation, cell transformation as well as induce epithelial–mesenchymal transition." (PMID 34270461, 2021). "In addition, we determined that homozygous carriers of the CCAT1 rs67085638 T allele exhibited increased BMI1 transcript levels compared to homozygous carriers of the CCAT1 rs67085638 C allele from primary GC tissues as well as in histopathologically confirmed cancer-free margin tissue." (PMID 34321511, 2021). "Inhibiting BMI1 can make cancer cells sensitive to chemotherapy through induction of AKT-mediated apoptosis pathway." (PMID 34270461, 2021). "Since SOX2, KLF4, and BMI1 are transcription factors which are mainly located in the nucleus of cancer cells, it was unlikely that circFAT1 regulated their expression directly." (PMID 34258151, 2021). "BMI1 overexpression has been reported in many cancers, where it controls proliferation and migration of neoplastic cells and also promotes apoptosis; its pharmacological inhibition increases sensitivity to chemotherapy treatments in some cancer types." (PMID 34316702, 2021). "BMI-1, a polycomb ring finger oncogene, is highly expressed in multiple cancer cells and is involved in cancer cell proliferation, invasion, and apoptosis." (PMID 34576269, 2021). "The development of small molecule inhibitors against BMI1 will therefore pave the way for therapies that not only target highly proliferative cancer cells, but also the slowly dividing, therapy-evading cancer stem-like cells (CSCs)." (PMID 33804165, 2021). "Here, we investigate the contribution of BMI1, given the established role of this epigenetic regulator in sustaining aggression in cancer." (PMID 33523558, 2021). "The exclusive recent list of potential candidate biomarkers includes molecules expressed by the cancer stem and stem-like cells, BMI-1 protein being one of them." (PMID 34199929, 2021).
cancer (continued). "BMI-1 plays a vital role in cancer cell proliferation, invasion/metastasis, chemo-sensitivity and patient survival." (PMID 35582010, 2021). "Western blotting was used to detect the expression of cancer stem cell markers Oct4, Bmi1, and Sox2 after the induction of EMT in gliospheres as well as after treatment with NC (2.5, 5.0, 7.5, and 10.0 μM) for 48 h." (PMID 33788424, 2021). "As an oncogene, Bmi1 changed some signaling pathways related to cancer in WB‐F344 oval cells and promoted the proliferation and invasion of WB‐F344 oval cells in vitro." (PMID 33639034, 2021). "BMI1 (B cell specific Moloney murine leukemia virus integration site 1) is an important biomarker of cancer stem cells (CSC)." (PMID 35053051, 2021). "In the meantime, SPP1 overexpression promotes the expression of KLF4, NANOG, SOX2, and BMI1, which were cancer stem cell markers." (PMID 33996808, 2021). "Several studies have suggested the overexpression of the BMI-1 gene as a predictive marker of cancer initiation." (PMID 34551814, 2021). "Altogether, these studies demonstrate that therapeutic blockade of IL-6R suppresses Bmi-1 function and inhibits cancer stemness." (PMID 34689150, 2021). "Strikingly, the TGFβ-induced expression of mesenchymal marker N-cadherin, EMT marker vimentin, and cancer stem cell marker Bmi1 was rescued by transient expression of La wildtype (LaWT) but not by the RCD activity-defective La mutant (LaΔRCD)." (PMID 33477794, 2021). "In particular, miR-340 appeared to be sponged by circ_001680, leading to an upregulation of BMI1 and to an increase of both the cancer stem cell (CSC) population and CPT11 resistance." (PMID 34503164, 2021). "The mRNA expression of several cancer stemness genes including BMI1, Sox2, Oct4, and c-Myc, was upregulated in A400 cells." (PMID 34681614, 2021). "As cancer stem cells are believed to be responsible for tumor recurrence and therapy resistance, a better understanding of the role for BMI1 in RB would be critical for tumor management and relapse control." (PMID 32840881, 2021). "BMI-1 expression is deregulated in cancer, resulting in the alteration of chromatin and gene transcription repression." (PMID 34199929, 2021). "Recent studies have reported that B cell-specific Moloney murine leukemia virus integration site 1 (BMI-1), a transcription factor involved in regulating cell cycle and apoptosis, is upregulated in various cancers and related to poor prognosis." (PMID 34551814, 2021). "Sox2, Oct4, and Bmi1 are effective markers of cancer stem cells, because they play important roles in the growth of cancer stem cells and promote the malignant progression of tumors." (PMID 33788424, 2021). "BMI1 is a promoter of stemness traits of cancer cells and represents a key mutual target linking miR-128 and miR-340, both suppressors of tumorigenesis in CRC." (PMID 34503164, 2021). "Bmi1 is also crucially involved in cancer-initiating cell maintenance and was found to be upregulated in recurrent MCL." (PMID 34502399, 2021). "Multiple researches have shown that BMI1 is involved in chemoresistance, while inhibiting BMI1 can make cancer cells sensitive to chemotherapy." (PMID 34270461, 2021). "Intriguingly, a study demonstrated that gene therapy targeting BMI1 can block chemoresistance in cancer cells, improving prognosis." (PMID 33804165, 2021). "Recent studies have demonstrated that BMI-1 plays a role as a cancer stemness marker and is involved in the functional regulation of CSCs." (PMID 34576269, 2021). "GSEA of murine C10 cells versus all other tumor epithelial cells demonstrated enrichment of stem cell signatures and target genes of the cancer stem cell gene BMI-1." (PMID 33854168, 2021). "Expression of LGR5 and BMI1 cancer stemness markers was significantly enhanced when cells were cultured under hypoxic conditions p<0.05." (PMID 34314381, 2021). "We examined the anti-cancer effects of two BMI-1 inhibitors (PTC596 and PTC209) in multiple cancer cells." (PMID 34576269, 2021).